CD4 (CD4 molecule)
Diseases named in the same sentence as CD4 in open-access papers (continued):
Sharing a sentence is not in itself a finding about the gene and the disease.
Opportunistic infection (1,199 papers, 2003 to 2026). An infection that is caused by a pathogen that would generally not be able to cause an infection in a host with a normal immune system. "Circulating CD4+ T-cell count is the gold-standard measure of immune injury and opportunistic infection risk in HIV infection and is tightly coupled with patient prognosis." (PMID 41601726, 2026). "HIV primarily targets the human immune system, especially CD4+ T lymphocytes, leading to progressive immune system dysfunction and rendering patients susceptible to severe opportunistic infections and malignancies." (PMID 42317333, 2026). "Use of cotrimoxazole preventive therapy (CPT), isoniazid preventive therapy (IPT), and opportunistic infection (OI) medications was each independently associated with higher odds of CD4 improvement." (PMID 41872881, 2026). "HIV infection is characterized by a reduced CD4+ T-lymphocyte count and an increased susceptibility to opportunistic infections." (PMID 41595295, 2026). "The progressive depletion of CD4+ T cells not only signifies immune deterioration but also serves as a critical marker for treatment outcomes and susceptibility to opportunistic infections in PLWH." (PMID 40704918, 2025). "Idiopathic CD4 lymphopenia (ICL) is a rare non–HIV-related syndrome, characterized by a reduced CD4 T-cell count and a predisposition to various opportunistic infections." (PMID 39866372, 2025). "HIV targets and destroys CD4+ T cells, which are crucial for an effective immune response, leading to severe immunodeficiency and an increased risk of opportunistic infections and cancers." (PMID 40432048, 2025). "A low CD4 count identifies patients at high risk not only for cryptococcosis but also for other opportunistic infections." (PMID 40198673, 2025). "Opportunistic infections prevalent in 46.6% of older adults; CD4 < 350 associated with 3.12x higher risk (CI: 2.29‐4.25)." (PMID 40843393, 2025). "The differential diagnosis of intracranial mass lesions in PLWH is broad, with the incidence of opportunistic infection (Mycobacterium tuberculosis, toxoplasmosis, Cryptococcus) inversely associated with CD4 T-lymphocyte count." (PMID 40951615, 2025). "When CD4 T cells and antigen-presenting cells count decrease meaningfully, the skin becomes susceptible to opportunistic infections and neoplastic diseases." (PMID 40002552, 2025). "High viral load and low CD4 counts associated with advanced HIV can lead to increased susceptibility to opportunistic infections, ultimately resulting in poorer clinical outcomes." (PMID 41210238, 2025). "The higher HIV-RNA, the higher infectiousness, and the lower CD4+ count, the higher the risk of opportunistic infection." (PMID 39944832, 2025). "Low immunity with low CD4 + T cells is associated with an increased risk of opportunistic infections, increasing the likelihood of antimicrobial use and hospitalization." (PMID 40493608, 2025). "She met the criteria for T1 due to extensive cutaneous lesions and lower extremity edema; I1 due to a CD4 count below 200 cells/mm3; and S1 based on systemic symptoms such as weight loss and signs of opportunistic infection." (PMID 40922874, 2025). "Steroid exerts a significant effect on the T cell-mediated immune response, especially CD4+ T cells responsible for infectious immunity, making patients more susceptible to opportunistic infections." (PMID 41210689, 2025). "HIV-positive individuals are at risk of opportunistic infections in the advanced stage of disease, defined as CD4 T cell counts <200 cells/mm3." (PMID 41375872, 2025). "Many people living with HIV have weakened immune systems due to the virus’ impact on CD4 T-cell counts and are therefore more susceptible to various opportunistic infections like TB." (PMID 39953390, 2025). "The national consolidated guidelines of 202015 outline that CD4 count should be measured to monitor susceptibility to opportunistic infections and eligibility for co-trimoxazole preventative therapy." (PMID 40356738, 2025).
Opportunistic infection (continued). "HIV-1 primarily targets CD4+ T lymphocytes, leading to a gradual collapse of cell-mediated immunity and increased susceptibility to opportunistic infections and neoplasms." (PMID 41009690, 2025). "HIV infection is characterized by progressive depletion of CD4+ T-lymphocytes, resulting in impaired cell-mediated immunity and heightened susceptibility to opportunistic infections and certain malignancies." (PMID 41374357, 2025). "In the presence of lymphadenopathy in these patients, low CD4 count and lymph nodes > 5 cm should quickly lead to lymph node biopsy in search for associated opportunistic infections or lymphoproliferative disorders." (PMID 40982488, 2025). "HIV-1 pathogenesis is characterized by a high rate of viral replication, immune evasion, and the gradual depletion of CD4+ T cells, resulting in a weakened immune response and increased susceptibility to opportunistic infections and malignancies." (PMID 40072080, 2025). "Bendamustine, a chemotherapy agent with both alkylating and purine analog properties, enhances the effects of anti-CD20 antibodies, leading to prolonged lymphopenia, especially CD4 + depletion, raising susceptibility to opportunistic infections." (PMID 41175237, 2025). "When CD4+ T cell counts fall below 200 cells/μl, patients are at high risk for severe opportunistic infections." (PMID 40989801, 2025). "Human Immunodeficiency Virus type 1 (HIV-1), the etiological agent of AIDS, primarily targets CD4+ T cells, macrophages, and dendritic cells, leading to progressive immune dysfunction and increased susceptibility to opportunistic infections and malignancies." (PMID 41009690, 2025). "The depletion of CD4+ T cells, caused by direct infection and bystander apoptosis, leads to immunosuppression, increasing vulnerability to opportunistic infections and malignancies." (PMID 40072080, 2025). "In the old animals, inability to restore CD4+ T cells was associated with a more profound immune suppression, opportunistic infections, and increased SIV-related mortality." (PMID 40662355, 2025). "Taken together, our study uncovered a previously unrecognized role of TRAP1 in CD4+ lymphocytopenia, conferring susceptibility to opportunistic infections." (PMID 39224595, 2024). "The hallmark of HIV infection is a gradual reduction in absolute CD4+ T-cell numbers, leading to compromised cellular immunity and increased susceptibility to opportunistic infections." (PMID 37821620, 2024). "This study showed that age ≥ 35 years, being single, baseline ART regimen with (AZT + 3TC + NVP), baseline CD4 cell count < 350 mm3, Tb-co infection, and opportunistic infection in the last 6 months were factors associated with virologic failure." (PMID 38915090, 2024). "Logistic regression analysis identified nutritional risk, duration of HIV infection, HbA1c, albumin, and CD4+ T cell counts as significant risk factors and predictors of opportunistic infections." (PMID 39866736, 2024). "The achievement and stability of normal CD4 count over long period of time is critical to optimal immune recovery, improved quality of life, lower risk of opportunistic infections and risk of mortality." (PMID 40809590, 2024). "A lower CD4 count is linked to a higher chance of developing opportunistic infections and a diminished tolerance to chemotherapy." (PMID 38961368, 2024). "Well known risk factors for cognitive disorders are opportunistic infections and low CD4+ T-cell counts; indeed, a late presentation of HIV infection can be associated with severe cognitive impairment." (PMID 38704619, 2024). "HIV infection leads to a decrease in CD4+ T cells, disruption of the structure and function of the intestinal mucosal barrier, and an increased probability of opportunistic infections, thereby increasing the risk of cardiovascular disease." (PMID 38387693, 2024).
Opportunistic infection (continued). "On the other hand, BDM increased the risk of opportunistic infections in association with CD4-positive lymphopenia due to specific cytotoxicity of BDM toward CD4-positive cells." (PMID 39348376, 2024). "The recovery of CD4 positively correlates with lower risk of opportunistic infections, disease progression and mortality." (PMID 40809590, 2024). "This study showed that client age, marital status, baseline ART regimen, baseline CD4 cell count, history of Tb-co infection, and opportunistic infection in the last 6 months were factors associated with virologic failure among clients on first-line ART." (PMID 38915090, 2024). "This increase, in turn, results in a reduced risk of developing opportunistic infections, particularly when CD4 levels reach higher thresholds." (PMID 38299523, 2024). "PcP is an opportunistic infection that occurs in patients suffering from CD4+ T cell response deficiency, which is the case in KTR, who are thus eligible for PcP prophylaxis." (PMID 38328616, 2024). "The records include age, gender, date of initiation of HAART, prevalence of opportunistic infections (OIs), date of diagnostic of first opportunistic infection, baseline CD4 count, WHO HIV stage, deaths, time of follow-up." (PMID 39687438, 2024). "Significant factors associated with opportunistic infections were being 50 years or older, having a CD4 count lower than 350, and having a hepatitis C virus co-infection." (PMID 38370863, 2024). "People with advanced human immunodeficiency virus with low CD4 T-cell counts, opportunistic infections, or associated inflammatory syndromes are at increased risk of clonal hematopoiesis." (PMID 38564303, 2024). "This stage begins to take a large toll on the individual’s immune system, as CD4 cells start to drop, putting the individual at high risk for developing several opportunistic infections." (PMID 39439637, 2024). "In HIV infection, the progressive depletion of CD4+ T cells leads to immunodeficiency and increased susceptibility to opportunistic infections." (PMID 38988810, 2024). "Initiation of ART among people living with HIV (PLWH) having a CD4 count ≤ 350cells/μl, produces poor immunological recovery, putting them at a high risk of opportunistic infections." (PMID 38627722, 2024). "The CD4 + cell count reflects the status of the immune system; thus, a reduction in CD4 + T lymphocyte counts predisposes patients to opportunistic infections." (PMID 38549051, 2024). "This reduction in CD4+ T cells predisposes individuals to opportunistic infections by viruses, encapsulated fungi, or mycobacteria, as well as to neoplasms." (PMID 38883060, 2024). "By identifying the factors associated with its occurrence, such as a low CD4 count, opportunistic infections, and delayed entry into the HIV program, healthcare professionals can anticipate the risk to patients and implement early action plans." (PMID 39364496, 2024). "HIV infection also causes a decline in CD4+ T cells, dampening the host’s immune responses and increasing the susceptibility of the host to opportunistic infections and tumorigenesis." (PMID 38891030, 2024). "Many previous studies have shown that CD4 T lymphocytes are highly associated with opportunistic infections, and the incidence can be variable in different geographical areas." (PMID 37887742, 2023). "In the older group, previous opportunistic infection and advanced age were associated with lower CD4 count." (PMID 38131882, 2023). "Treatment of HIV-infected children with ART leads to immune cell reconstitution, as shown by the increase in CD4 cell counts, decreased risk of opportunistic infection, and improved survival." (PMID 38087261, 2023). "We also found that patients with a lag time of less than 1 month were more likely to have late ART initiation, and that patients with low CD4 cell count and opportunistic infection at ART initiation were associated with reduced risk of delayed ART initiation." (PMID 37416802, 2023).
Opportunistic infection (continued). "Persons initiating ART at very low CD4+ cell counts are at higher risk of opportunistic infections and death." (PMID 36826348, 2023). "The gastrointestinal tract is a major site of HIV replication, which results in the massive depletion of lamina propria CD4 T cells during acute infection, which leaves affected individuals mortally susceptible to opportunistic infections." (PMID 36851577, 2023). "In the older subgroup (aged over 60 years old), factors associated with CD4 count improvement were age and previous opportunistic infections, underlining the importance of an early diagnosis and treatment, especially in the frailest populations." (PMID 38131882, 2023). "So, having low CD4 counts below a threshold at baseline increases the risk of opportunistic infection." (PMID 38033131, 2023). "We found numerous features of HIV disease control, including the presence of opportunistic infections, the presence of side effects and lower CD4 count were strongly associated with HRQoL." (PMID 37605150, 2023). "HIV-associated wasting accompanying advanced CD4 cell depletion is characterized by an increase in basal metabolism, which can increase further during opportunistic infections." (PMID 37060030, 2023). "Living in a rural, poor adherence, lower CD4 count, and recent opportunistic infection were independent risk factors associated with virological failure." (PMID 38033131, 2023). "If people living with HIV did not take ART their viral load is more likely to increase, leading to lower CD4-count and an increase the risk of developing opportunistic infection." (PMID 37917729, 2023). "Immunocompromised patients with lower CD4 cell counts are at a higher risk of opportunistic infections, leading to increased viral replication and a higher risk of drug resistance." (PMID 37884997, 2023). "A CTCC level of less than 200 cells/μl and a CD4/CD8 ratio below 0.20 were associated with a significant increase in HIV opportunistic infections." (PMID 38102603, 2023). "PLWH that have a CD4 count less than 200 cells/μl have an increased risk of opportunistic infections." (PMID 37424787, 2023). "The CD4 + T-cell count reflects the immune status and risk of opportunistic infections at the time of treatment for PLHIV." (PMID 37660054, 2023). "Nevertheless, CD4 count remains the best measurement of patients’ immune and clinical status, the risk of opportunistic infections, and diagnosis decision-making, particularly for patients with AHD." (PMID 37608300, 2023). "Patients with decreased CD4+ T cell counts were associated with an increased risk of various opportunistic infections because of immunosuppression." (PMID 37887742, 2023). "Previous opportunistic infection (OR 0.1378, CI 0.01913 to 0.7464) and advanced age (OR 0.7879, CI 0.6372 to 0.9386) were associated with a lower CD4 count (<500 cells/mm3)." (PMID 38131882, 2023). "Many studies have established a clear association between lower total CD4+ cell counts and the development of opportunistic infections in HIV subjects." (PMID 36826348, 2023). "Our first key finding was that poor disease control and markers of advanced HIV: namely high VL in South Africa, low CD4 count in Uganda, and opportunistic infection in both countries, were associated with lower HRQoL." (PMID 37605150, 2023). "This study reveals complex associations between spirometric parameters and CD4 count, viral load, and opportunistic infections in children with HIV." (PMID 38022158, 2023). "Despite antiretroviral therapy (ART) scale‐up among people living with HIV (PLHIV), those with advanced HIV disease (AHD) (defined in adults as CD4 count <200 cells/mm3 or clinical stage 3 or 4), remain at high risk of death from opportunistic infections." (PMID 36880429, 2023). "Peripheral CD4+ T-cell counts predict disease progression in untreated PWH19,20, and decreasing CD4+ T-cell counts are associated with the onset of opportunistic infections and AIDS21." (PMID 36813761, 2023).
Opportunistic infection (continued). "This can be explained by the fact that children with treatment failure are at risk for viral load increment and the CD4 cell count continues to drop, which leads to the development of an opportunistic infection like SAM." (PMID 35031007, 2022). "As a chronic RNA virus, the pathogenic mechanism of HIV is to attack the helper T lymphocyte, CD4 cell, causing damage to the body’s immune functions and various opportunistic infections." (PMID 35129067, 2022). "Clinical staging of HIV disease and the relative risk of developing opportunistic infections have historically relied on CD4+ T-lymphocyte counts." (PMID 35814692, 2022). "Human immunodeficiency virus (HIV) reduces immunity by lowering the number and functional efficacy of CD4 helper lymphocytes, leading to a greater risk of opportunistic infections and other infections." (PMID 35070354, 2022). "HIV-infected patients with a CD4+ lymphocyte count below 100 cells/mm3 present a higher risk of clinically overt opportunistic infections, including T. gondii-induced encephalitis and ocular toxoplasmosis." (PMID 35160090, 2022). "The reduction of CD4 count decreases the immunity of patients, exposing them to opportunistic infections and at high risk of developing serious illnesses leading to death." (PMID 36467882, 2022). "In multivariable analysis, VF was associated with opportunistic infection (aOR, 4.84; 95% CI, 1.77–13.24), lower CD4 count (aOR 4.15; 95% CI, 1.98–8.71) and lower weight at first-line failure (aOR, 2.67; 95% CI, 1.33–5.34)." (PMID 36528762, 2022). "Poor ART adherence, advanced WHO clinical staging, opportunistic infections, and low level of CD4 cell counts increased the risk of treatment failure." (PMID 35421084, 2022). "The successive loss of peripheral blood CD4+ T cells can result in the development of opportunistic infections." (PMID 36298842, 2022). "This leads to declining of CD4 cell count which will end up with high risk of developing opportunistic infections including TB." (PMID 35921384, 2022). "Looking into the histogram composition at the genus level in depth, what is worth noticing is a sharp increase in Candida in the low-CD4 + T-cell group, indicating a high risk of opportunistic infection." (PMID 36016433, 2022). "At the genus level, Candida was significantly increased in the low CD4+ T-cell group, indicating a high risk of opportunistic infection." (PMID 36439143, 2022). "A higher susceptibility to opportunistic infections (OIs) due to the lower immune status (indicated by the low CD4 levels) can justify this finding." (PMID 34890421, 2021). "The switch in therapy was due to significantly low CD4+ T lymphocyte count ≤65 cells/ul (normal range 490–1740 cells/ul), after discussing the results with the patients and the potential risk for opportunistic infections including cryptococcal infections." (PMID 33530945, 2021). "A weakened immune system and a higher risk of opportunistic infections can be seen in people who have low CD4 + levels." (PMID 33384873, 2021). "According to the patients’ CD4+ cell recovery within the first year on cART and the resulting sustained risk of opportunistic infections, they were classified into three groups [< 50 (n = 67), 50–200 (n = 115) and > 200 CD4+ cells/μl (n = 119),]." (PMID 33537915, 2021). "Impaired quantitative and functional recovery of T cells (in particular, CD4+ T lymphocytes was directly associated with an increased risk of opportunistic infections, relapses, and overall unfavorable clinical outcomes." (PMID 34305933, 2021). "After a discussion with patients, a decision was made to switch treatments due to concerns for the risk of opportunistic infections including cryptococcal infections given the significantly low CD4+ T lymphocyte count." (PMID 33530945, 2021). "CD4 count is widely used to assess the extent of immunodeficiency and risk for opportunistic infections and mortality in the management of HIV infection." (PMID 33784358, 2021).